CSF1R (colony stimulating factor 1 receptor)
Diseases named in the same sentence as CSF1R in open-access papers (continued):
Sharing a sentence is not in itself a finding about the gene and the disease.
osteopetrosis (22 papers, 2011 to 2025). Osteopetrosis, also known as marble bone disease, is a descriptive term that refers to a group of rare, heritable disorders of the skeleton characterized by increased bone density on radiographs. "Mutations in CSF1R can impair osteoclast function, resulting in osteopetrosis, which is consistent with our research findings." (PMID 39865310, 2025). "We found that genes associated with osteopetrosis have undergone positive selection (CSF1R and LRRK1) or pseudogenized (FAM111A and IGSF23) in the African manatee, potentially contributing to the dense bone formation." (PMID 39092175, 2024). "The definitive phenotype of Csf1 and Csf1r mutations in mice and rats is osteoclast deficiency and osteopetrosis." (PMID 35333324, 2022). "Biallelic recessive loss-of-function mutations in mouse, rat and human CSF1R are causally linked to osteopetrosis and postnatal developmental abnormalities." (PMID 35333324, 2022). "Homozygous infants with CSF1R deletion suffer death within 1 year of birth, accompanied by microglial deficiency, macrocephaly, and osteopetrosis." (PMID 34955818, 2021). "The only definitive human homozygous CSF1R null mutation described thus far was associated with severe osteopetrosis, brain developmental defects and infant mortality." (PMID 34081701, 2021). "Osteopetrosis in op/op and Csf1r-deficient mice is attributed to an almost complete deficiency in bone-resorbing OCL." (PMID 24652541, 2014). "The homozygous mutations in CSF1R are associated with severe osteopetrosis in rats and mice." (PMID 39092175, 2024). "These investigators subsequently demonstrated that the osteopetrosis phenotype of CSF-1- and CSF1R-deficient mice could be replicated by post-natal administration of a neutralising anti-CSF-1 antibody." (PMID 21738673, 2011). "Generalized osteopetrosis with severe cerebral malformationhas been reported in consanguineous patients withmutations in the CSF1R gene who had osteopetrosis andcerebral malformations." (PMID 37465191, 2023). "Systemic Csf1r-knockout mice can exhibit osteopetrosis, reduction in marrow hematopoiesis, and defection in reproductive function, impairment in olfactory capacity, and reduction in mononuclear phagocyte, including microglia." (PMID 34955818, 2021). "A common trait between Csf1r−/− rats and mice is increased bone density (osteopetrosis) attributed to either a reduction (mice) or complete absence (rats) of bone-resorbing osteoclasts." (PMID 30249809, 2018). "In osteopetrosis with osteoclast deficiency, osteoclastdifferentiation is impaired due to mutations in the TNFSF11and TNFRSF11A genes encoding RANKL and its receptorRANK, respectively, or in the CSF1R gene encoding M- CSF." (PMID 37465191, 2023). "Recently, patients carrying homozygous mutations in CSF1R and presenting with both leukodystrophy and osteopetrosis, phenotypes attributed to an absence of TRMs in the brain and bone, have been described." (PMID 32367800, 2020). "Homozygous mutations in CSF1R cause severe congenital brain disease with osteopetrosis, and absence of microglia." (PMID 32367800, 2020). "Phenotypes of the Csf1 or Csf1r mutant mice include increased bone density (osteopetrosis), abnormalities of the sensory nervous system, global defects in brain development, infertility, failure of pancreatic β cell development, and severe postnatal growth retardation (reviewed in Ref." (PMID 30249809, 2018). "In addition, a heterozygous truncating mutation in the colony-stimulating factor 1 receptor (CSF1R) gene, which encodes the macrophage colony-stimulating factor 1 receptor (M-CSF), was reported in the consanguineous parents of two deceased siblings showing osteopetrosis and brain malformations." (PMID 33970241, 2021).
osteopetrosis (continued). "In contrast to CSF1R-deficient mice, FIRE-deficient mice are healthy and fertile without growth, neurological, or developmental abnormalities such as osteopetrosis and failure of tooth eruption, suggesting that the FIRE is not required for Csf1r expression in all types of myeloid cells." (PMID 32801364, 2020).
Stroke (22 papers, 2019 to 2026). Sudden impairment of blood flow to a part of the brain due to occlusion or rupture of an artery to the brain. "Further investigation was needed to determine the role of microglia in long‐term neurological impairment after stroke; therefore, the colony‐stimulating factor 1 receptor (CSF1R) inhibitor PLX5622 was used to deplete microglia in mice." (PMID 39088351, 2024). "Increased microglial numbers are also observed in the chronic post‐stroke response in white matter and in this condition, depletion of microglia by shRNA targeting of Csf1r has protective effects on white matter integrity and cognitive abilities." (PMID 37909242, 2024). "The Csf-Csf1r interaction plays a very important role in the differentiation regulation of microglia under both homeostatic and stroke conditions." (PMID 37199734, 2023). "Few studies in stroke models have investigated how microglia affect outcomes after CSF-1R inhibition." (PMID 35115368, 2022). "We investigated the therapeutic effect of microglia repopulation on stroke outcomes by inhibiting CSF-1R between days 3 and 7 after ischemia." (PMID 35115368, 2022). "Neuronal cell death can decrease colony stimulating factor 1 receptor (CSF1R) ligand IL-34 to deplete microglia, but deficiencies of CX3CR1 and CD200 after cell death activate microglia after stroke." (PMID 34502395, 2021). "In some models of acquired epilepsies, as well as in models of brain injury by trauma or stroke, drastic reductions in microglial populations with CSF1R inhibitors were shown to either improve or aggravate pathological consequences." (PMID 34149593, 2021). "Three weeks post-stroke, diabetic animals had an increase in residential microglia compared to sham animals and CSF1R KD resulted in a drastic 94% knockdown as measured by flow cytometry." (PMID 32345303, 2020). "The inhibition of colony-stimulating factor 1 receptor (CSF1R) which especially expressed in microglia/macrophage exerted neuroprotection in stroke." (PMID 32908485, 2020). "The residual IBA-1+ cells measured in IHC of the CSF1R silenced animals actually derived from the infiltrating macrophages, as the injection only lowered this population by 74% post-stroke when evaluated by flow cytometry." (PMID 32345303, 2020). "In our study, the CSF1R pathway was activated in stroke model mice, with CSF1R and Iba1 protein expressions being upregulated." (PMID 33192177, 2020). "CSF1R silencing also lowered the number of pro-inflammatory infiltrating macrophages which too were chronically elevated after a stroke." (PMID 32345303, 2020). "CSF1R silencing was able to lower the presence of inflammatory cells and halt a consequence of chronic inflammation after stroke." (PMID 32345303, 2020). "Although CSF1R silencing has been reported to exacerbate stroke injury in previous experimental stroke studies, it actually lowered inflammation and improved survival and cognition when diabetes was present." (PMID 32345303, 2020). "The upregulation of CSF1R expression in the WT+stroke group in comparison with the WT group indicated CSF1R signal activation (∗∗∗P < 0.001)." (PMID 33192177, 2020). "CSF1R silencing preserved the myelination in the CTX post-stroke, as the neurons were significantly more myelinated compared to the NTC." (PMID 32345303, 2020). "Our study is the first to evaluate the impact of CSF1R silencing on longer-term stroke behavioral outcomes under a comorbid neuroinflammatory condition, diabetes." (PMID 32345303, 2020). "Similarly, in an adult MCAO stroke model, removing microglia via chronic treatment with the CSF1R antagonist PLX3397 increased stroke lesion volume and worsened functional deficits." (PMID 40558537, 2025). "Altogether, this study highlighted the renewal of the microglia and macrophage compartment with CSF-1R inhibitor as a possible new immunomodulatory treatment paradigm after stroke that might be tracked by 18F-DPA-714 PET imaging." (PMID 35115368, 2022).
Stroke (continued). "Nevertheless, long-term depletion of CSF-1R resulted in microglial elimination from the CNS, and administration of CSF-1R antagonists over 7 consecutive days reversibly depleted 90% microglia, leading to the increased infarct size after stroke." (PMID 33281816, 2020). "No theory has suggested a single pathway underlying stroke neuropathology to account for CSF1R inhibitor regulation on microglia." (PMID 32908485, 2020). "A study utilizing oral administration of PLX3397 to silence the CSF1R in rats prior to stroke reported that it exacerbated stroke severity and actually increased the infarct size at 3 days by increasing the production of inflammatory mediators by astrocytes (IL-1b, iNOS, IL-6)." (PMID 32345303, 2020). "Furthermore, we found that stroke induced a high expression of CSF1R, which is closely related to microglial proliferation." (PMID 33177990, 2020). "Although CSF1R silencing lowered the presence of inflammatory cells to alleviate inflammation, the anti-inflammatory microglia have been shown to play a significant role in remyelination post-stroke." (PMID 32345303, 2020). "Also, CSF1R expression was further downregulated in the WT+K+stroke+TP group when compared with both the WT+stroke+TP and WT+stroke+K groups (^^^P < 0.001)." (PMID 33192177, 2020). "CSF1R expression was significantly decreased after ki20227 treatment, suggesting that stroke-related microglial proliferation may be dependent on the CSF1R signaling pathway." (PMID 33177990, 2020). "However, ki20227 treatment exacerbated neurodegeneration after stroke, which suggested that CSF1R is necessary for the recovery of neurons damaged by stroke." (PMID 33177990, 2020). "Microglia were depleted between days 3 and 7 post-stroke using PLX5622, a colony-stimulating factor 1 receptor inhibitor." (PMID 42293323, 2026). "We found that the expression levels of some chemokines and cytokine receptors, such as CSF1R, CSF1, CCL3, CD4, and CCR2, were significantly different in ki20227-treated stroke mice compared to vehicle-treated stroke mice." (PMID 33177990, 2020). "Conversely, administration of the colony stimulating factor-1 receptor (CSF-1R) inhibitor, PLX3397, in a mouse model of stroke eliminated microglia, resulting in increased infarct size, neuronal signaling dysregulation, and cell death, which was reversed markedly by microglial repopulation." (PMID 38550920, 2024). "Also, TP promoted the neuroprotective effect of Ki20227 by inhibiting CSF1R expression and upregulating BDNF, Erk1/2, and autophagy protein expressions in stroke mice." (PMID 33192177, 2020). "To date, no study on repopulation and/or short-term CSF-1R inhibition in stroke has been reported." (PMID 34950148, 2021). "Similarly, neither the combined treatment of TP and CSF1R inhibitor in cerebral ischemia nor its relationship to BDNF/autophagic pathways in the stroke model has been explored." (PMID 33192177, 2020).
hepatocellular carcinoma (21 papers, 2017 to 2025). A malignant tumor that arises from hepatocytes. "PLX3397, a CSF-1R inhibitor, promotes the polarization of TAMs from an M2 phenotype to an M1 phenotype, delaying tumor growth and improving survival in hepatoma models." (PMID 40764998, 2025). "High expression of secreted OPN in hepatoma stimulates colony-stimulating factor 1 (CSF1)/CSF1R activation in macrophage which further increases PD-1 expression in hepatoma cells." (PMID 36906534, 2023). "CSF1R expression in macrophages serves a pivotal role in the interaction between macrophages and hepatoma cells." (PMID 32724427, 2020). "Overexpression of CSF-1R was observed in many human cancer types, including prostate, breast, and hepatocellular carcinoma." (PMID 29228668, 2017). "Recent investigations into hepatocellular carcinoma have revealed that osteopontin (OPN) facilitates the M2-like polarization of macrophages and induces PD-L1 expression in hepatocellular carcinoma by activating the colony-stimulating factor-1 (CSF1)/CSF1 receptor (CSF1R) pathway." (PMID 38273373, 2024). "The density of CSF-1R+ TAMs in tumors correlates with poor outcomes in many tumor types, including colon adenocarcinoma, pancreatic cancer, classical Hodgkin lymphoma, leiomyosarcoma, hepatocellular carcinoma and breast cancer." (PMID 37114134, 2023). "In a study performed with a murine model of hepatocellular carcinoma, treatment with a CSF1R inhibitor resulted in increased CD8 infiltration accompanied by a reduction in MDSCs, a profile similar to what we observed in our study with the MC38 CSF1 knockout model." (PMID 37505292, 2023). "Importantly, cooperation between anti-PD-L1 therapy and the CSF-1R inhibitor PLX3397 has been recently described in a mouse model of hepatocellular carcinoma." (PMID 33920699, 2021). "Pointing at the overexpression of CSF-1R on the edge of hepatocellular carcinoma TAMs and monocytes, an ultrasonic nanoprobe (NBCSF-1R) conjugated with CSF-1R antibody emerged." (PMID 36678773, 2022). "In hepatocellular carcinoma (HCC), the OPN/CSF1/CSF1R axis plays a critical role in the immunosuppressive nature of the HCC microenvironment." (PMID 34423566, 2021). "Excess osteopontin (OPN) from hepatoma cells stimulates macrophages to secrete CSF1, through PI3K-AKT-NF-κB pathway, to bind to colony-stimulating factor-1 receptor (CSF1-R) on macrophages." (PMID 33344447, 2020). "Via CSF1‐R and CD138, IL‐34 promoted the proliferation and migration of hepatoma cells, and contributed to the activation of ERK and STAT3 pathways and the upregulation of Bcl‐xl and c‐Myc mediated by HBX." (PMID 31621133, 2019). "In addition, osteopontin overexpression upregulates PD-L1 expression in hepatocellular carcinoma cells by activating the CSF1–CSF1R pathway in macrophages, and blockage of CSF1/CSF1R prevents TAM trafficking." (PMID 31474227, 2019). "The application of CSF1-R inhibitor can significantly inhibit the infiltration of TAMs in tumor and increase the infiltration and killing activity of CD8+ T lymphocytes in tumor, which reshapes TME of hepatocellular carcinoma and enhances the efficacy of PD-L1 antibody." (PMID 33344447, 2020). "Whether CSF1R expression is regulated by DNA methylation in hepatocellular carcinoma (HCC) has not been fully elucidated." (PMID 32724427, 2020). "In hepatocellular carcinoma (HCC), CSF1/CSF1R blockade has been reported to serve a critical role in the immunosuppressive nature of TMEs." (PMID 32724427, 2020).
leukodystrophy (21 papers, 2015 to 2025). Leukodystrophies are a group of rare, progressive, metabolic, genetic diseases that affect the brain, spinal cord and often the peripheral nerves. "This case report describes the medication-focused individualized application of existing precision tools for a patient with CSF1R gene mutation and leukodystrophy following allogeneic hematopoietic stem cell transplantation (allo-HSCT)." (PMID 41394144, 2025). "The absence of microglia in mice with a hypomorphic Csf1r mutation also leads to progressive demyelination, which has been analysed as a model for leukodystrophy associated with human CSF1R mutation." (PMID 40533345, 2025). "In view of the family history, genetics panels were ordered for autosomal dominant Alzheimer’s disease, frontotemporal dementia, and leukodystrophy (that included testing for CSF1R variants)." (PMID 39217398, 2024). "This leukodystrophy is caused by mutations in the CSF1R (Colony Stimulating Factor 1 Receptor) gene." (PMID 35976293, 2022). "Leukodystrophies related to bi-allelic loss-of-function mutations in CSF1R, TREM2, TYROBP, LRRC33/NRROS or USP18 can be categorized as primary microgliopathies." (PMID 34282843, 2021). "In this study, we found that CSF1R mutations account for approximately 10% of adult onset leukodystrophies in a mixed cohort from the UK, Greece and Ireland." (PMID 25935893, 2016). "Following the algorithm approach to adult-onset leukodystrophies of Alturkustani and colleagues, we finally favored an adult-onset leukoencephalopathy/leukodystrophy with axonal spheroids (ALAS) related to CSF1R mutation." (PMID 26141177, 2015). "We report a new family with autosomal dominant inheritance of a late onset rapidly progressive leukodystrophy in which exome sequencing has revealed a novel mutation p.R782G in the Colony-Stimulating Factor 1 Receptor gene (CSF1R)." (PMID 25975230, 2015). "In addition, microglia maintain CNS homeostasis, and alterations in their function caused by deletions or mutations in TREM2 or the colony-stimulating factor 1 receptor (CSF1R) cause neurodegeneration or leukodystrophies, respectively." (PMID 39295865, 2024). "Altogether, these findings strongly suggest that microglial depletion or loss of homeostatic microglia, which may precede the onset of symptoms by many years, may be a key pathogenic initiating event in CSF1R-related leukodystrophy." (PMID 34282843, 2021). "Thus, CSF1R-related autophagy dysfunction and microglia loss may be early or initial pathogenic events contributing to leukodystrophy." (PMID 31827782, 2019). "Examples discussed in this review include polycystic lipomembranous osteodysplasia with sclerosing leukoencephalopathy and CSF1R-related leukodystrophy." (PMID 41315317, 2025). "We here review the roles of each of these cytokines in the CNS and how they contribute to the development of disease in a mouse model of CSF-1R-related leukodystrophy." (PMID 37964794, 2023). "The following section discusses the Csf1r+/− model of CSF-1 receptor-related leukodystrophy and how it can contribute to our understanding of the role of growth factor and cytokine receptors in demyelinating disease." (PMID 37964794, 2023). "Future investigations on potential functional correlations between CSF1R and AARS2 may shed light on whether and how CSF1R and AARS2 mutations lead to leukodystrophy through common molecular mechanisms." (PMID 34867307, 2021). "Our findings here provide insight into the mechanism that could also underlie the absence of microglia in CSF1R-related leukodystrophy and could help predict the effects on other TRM populations in response to CSF1R mutations or pharmacological inhibition." (PMID 32367800, 2020). "It is intriguing why these two seemingly unrelated genes, CSF1R and AARS2, give rise to the same leukodystrophy." (PMID 34867307, 2021).
leukodystrophy (continued). "Given the neuropathologic diagnosis of ALSP and negative results on standard genetic testing for leukodystrophy, we conducted both short-read whole-exome sequencing and long-read sequencing focusing on the CSF1R gene." (PMID 39217398, 2024). "Standard genetic testing for a leukodystrophy panel, including CSF1R, yielded negative results." (PMID 39217398, 2024).